B3GNT3 (UDP-GlcNAc:betaGal beta-1,3-N-acetylglucosaminyltransferase 3)
Diseases named in the same sentence as B3GNT3 in open-access papers (continued):
Sharing a sentence is not in itself a finding about the gene and the disease.
tumor (29 papers, 2015 to 2026). "B3GNT3, a critical gene included in the model, is associated with the tumor immune microenvironment and the prognosis of ESCC." (PMID 38818465, 2024). "B3GNT3 was significantly downregulated in ESCC tumor tissues and negatively associated with lymph node metastasis." (PMID 38818465, 2024). "In our study, the GSEA showed that the transcriptomes of LUAD patients with high levels of LAD1 and B3GNT3 were strongly associated with the tumor microenvironment, suggesting that they cooperated to build the tumor microenvironment." (PMID 36613882, 2022). "We found 6 hub genes in DEGs that overlapped with the tumor-related modules, and the overexpression level of B3GNT3 was significantly associated with the worse OS (overall survival) of the EGFR-MT LUAD patients (p < 0.05)." (PMID 34868228, 2021). "B3GNT3 overexpression was observed in PC tissue and was associated with larger tumor sizes, higher histologic grades, and poorer overall survival (OS)." (PMID 33316775, 2020). "Potential associations between the expression of B3GNT3 and tumor immunity were mainly analyzed by single-sample gene set enrichment analysis (ssGSEA) and immunofluorescence in tissue microarray (TMA)." (PMID 33316775, 2020). "The ESTIMATE algorithm showed that high levels of B3GNT3 expression were associated with increased tumor purity, but decreased immune score, suggesting that B3GNT3 overexpression may promote immunosuppression in PC." (PMID 33316775, 2020). "Because both CD44v6 and sLea are implicated in the tumor metastasis process, B3GNT3 may be involved in the possible modification of CD44 for sLea in PCSCs." (PMID 30466404, 2018). "Accumulating evidence suggested that tumor cell migration and metastasis may share similar mechanisms with lymphocyte trafficking, which support our results that the upregulation of B3GNT3 may cause lymph node metastasis." (PMID 26709519, 2015). "In this study, mRNA-seq revealed that the immunosuppressive state in the tumor microenvironment of ESCC deteriorated with tumor progression, suggesting that B3GNT3 plays a potential role in the immunoreaction of ESCA." (PMID 36995820, 2023). "Meanwhile, B3GNT3 expression was significantly upregulated in the tumor parts compared with its expression in the normal ones in the GSE31210 database." (PMID 36613882, 2022). "B3GNT3 was identified as one of the glycosyltransferases of PD-L1, whereas B3GNT3-downregulation enhanced cytotoxic T-cell-mediated anti-tumor immunity." (PMID 35538152, 2022). "Knocking out B3gnt3 in mouse breast cancer cells conferred a decrease in tumor PD-L1 expression and, therefore, potentiated tumor rejection." (PMID 34064396, 2021). "B3GNT3 was overexpressed in LUAD, and its expression level was positively associated with tumor stage, which suggested that B3GNT3 played an important role in tumor carcinogenesis and prognosis." (PMID 33996569, 2021). "From the scRNA-seq result, we noticed that the expression level of B3GNT3 in tumor cell was positively correlated with the proportion of the exhausted CD8+ T cell (r = 0.95, P = 0.0012)." (PMID 33996569, 2021). "B3GNT3 was overexpressed in tumor tissues (P < 0.0001) according to GSE62452 dataset and GSE60979 dataset." (PMID 33316775, 2020). "Some of the glycoTs genes such as GCNT3, GALNT5, FUT3, B3GNT6 and B3GNT3 were more than 19-fold overexpressed in tumour samples." (PMID 32203219, 2020). "B3GNT3 overexpression significantly correlated with decreased infiltration of tumor infiltrating lymphocytes (TILs), especially CD8+ T cells." (PMID 33316775, 2020). "B3GNT3 expression was significantly correlated with tumor size (P = 0.017) and histologic grade (P = 0.001)." (PMID 33316775, 2020). "In this study, we aimed to delineate the biological role of B3GNT3 during pancreatic tumorigenesis and tumor immunity." (PMID 33316775, 2020).
tumor (continued). "Cerhan found that B3GNT3 is related to immune function and inflammation, and plays an important role in lymphocyte trafficking and migration, which lead to tumor cell survival and metastasis in NHL." (PMID 26709519, 2015). "Considering the important role of NF-κB in tumor immunity, B3GNT3 may regulate tumor immunity through multiple pathways." (PMID 36561746, 2022). "Moreover, it was reported that B3GNT3 downregulation enhances the anti-tumor immunity of cytotoxic T cells in triple-negative breast cancer." (PMID 33316775, 2020). "Our study also identified the novel role of B3GNT3 in tumor immunity of PC." (PMID 33316775, 2020). "Moreover, in GSE28735 dataset, B3GNT3 expression in tumor tissues was significantly upregulated compared with that in the adjacent non-tumor tissues (P < 0.0001)." (PMID 33316775, 2020). "Additionally, B3GNT3 has been proposed as an independent prognostic factor of better survival outcome after the evaluation of its expression in NB tumor tissues." (PMID 30344930, 2018). "In addition, the correlation analysis showed that high expression of 4F2hc was more frequent in PDAC with poor differentiation, and positive protein expression of B3GNT3 was more significantly associated with American Joint Committee on Cancer (AJCC) III-IV stage and tumor stage in T1-2." (PMID 37479744, 2023). "The expression levels of key glycosyltransferases, such as B3GNT3, ALG3, and GALNT14, along with tumor GAG content and proteoglycan expression patterns, can guide patient stratification and therapeutic decision-making." (PMID 41008983, 2025). "B3GNT3, MACC1, and NELL2 showed significantly higher expression in normal tissues than in tumor tissues." (PMID 38818465, 2024). "The Wilcoxon Rank Sum test revealed that ALG1L2, B3GNT3, and B3GNT8 were expressed at higher levels in tumor tissues, while HS6ST3 and ST8SIA5 were expressed at lower levels in tumor tissues (all P < 0.01)." (PMID 38097951, 2023). "In tumor tissues, the expression of ST3GAL6 was found to be notably reduced, whereas the expression levels of B3GALT2, ABO FUT3, B3GNT3, and B3GNT5 were observed to be significantly elevated." (PMID 37781041, 2023). "B3GNT3 overexpression inhibits CD8+ T-cell infiltration in pancreatic cancer and promotes tumor progression." (PMID 36561746, 2022). "Analysis of TCGA-LIHC data revealed elevated expression of SOX9, DCN, GPC3, and B3GNT3 in tumor tissues versus non-tumor counterparts." (PMID 41268541, 2025). "Besides, we compared the expression of DRGGs between HCC tissues and normal samples and found that most genes, such as AGRN, B3GNT3 and FLNA, were highly expressed in tumor tissues, resulting in a worse patient prognosis." (PMID 37680641, 2023). "According to the HPA database, the protein levels of the B3GNT3 gene were substantially higher in tumor tissues than in normal tissues." (PMID 34868228, 2021). "B3GNT3 was shown to be upregulated in tumor tissues as opposed to normal tissues in our sample, with a strong link to EGFR-MT LUAD." (PMID 34868228, 2021). "Thus, we propose that B3GNT3 overexpression induces SMAD4 inactivation and promotes tumor growth and metastasis through TGF-β signaling pathway." (PMID 33316775, 2020). "Therefore, in the context of ESCC, low expression of B3GNT3 may promote the accumulation of M2 macrophages, thereby influencing the epithelial-mesenchymal transition process and WNT pathway, ultimately facilitating tumor cell infiltration and metastasis." (PMID 38818465, 2024).
cancer (19 papers, 2015 to 2025). A tumor composed of atypical neoplastic, often pleomorphic cells that invade other tissues. "Other studies have also associated differential B3gnt3 expression levels with development of many other types of cancers." (PMID 38436597, 2024). "In this study, B3GNT3 expression was significantly upregulated in cancer tissues in association with ESCA adjacent tissues or normal esophageal tissues, which is consistent with previous findings." (PMID 36995820, 2023). "Consistent with the GSEA of LAD1, the transcriptomics of LUAD patients with a high level of B3GNT3 were associated with cancer metastasis, EMT, and poor prognosis." (PMID 36613882, 2022). "Previous reports also confirmed that B3GNT3 overexpression was associated with shorter survival of patients in the cervical and non-small lung cell cancers." (PMID 31379917, 2019). "GALNT3 and B3GNT3 have been implicated in the regulation of tumorigenesis in many cancers." (PMID 30466404, 2018). "B3GNT3 has been implicated as an important element in the development of certain cancers." (PMID 26709519, 2015). "N-glycosylation of 4F2hc by B3GNT3, immunogenic ferroptosis induced by ALG3 deficiency, and the GAG-mediated lipoprotein uptake pathway exemplify the sophisticated ways in which cancer cells exploit the glycosylation machinery to evade ferroptotic cell death." (PMID 41008983, 2025). "The β3GlcNAcT family members, including B3GNT3, are closely correlated with the development and progression of various cancers." (PMID 36613882, 2022). "Previous studies have reported a critical role of B3GNT3 in various malignant tumors." (PMID 36575396, 2022). "This suggests that B3GNT3 may behave differently when expressed in malignant cells of different cancers." (PMID 32203219, 2020). "Their study suggested that B3GNT3 plays an oncogenic role in certain types of cancer." (PMID 26709519, 2015). "The relationship between glycosyltransferase B3GNT3 and carbohydrate sulfotransferase CHST4 in HF remains unreported; however, both enzymes exhibit upregulated expression in cancers." (PMID 41268541, 2025). "As for elongation, B3GNT3, B3GNT4, and GCNT3 were highly expressed in both cancer types (LUAD and LUSC)." (PMID 40718829, 2025). "The GSEA findings showed that upregulated B3GNT3 was statistically correlated with cell proliferation, cell cycle, cancer metastasis, and EMT in cancers." (PMID 36613882, 2022). "Lastly, we also tested PODO447 recognition of cancer-associated STn (KI ST6GALNAC1/KO COSMC) and core 3 O-glycans (KI B3GNT3/KO COSMC) and observed no Ab binding to either of these structures." (PMID 35600398, 2022).
adenocarcinoma (1 paper, 2015). A common cancer characterized by the presence of malignant glandular cells. "In particular, expression of the GlcNAc transferases GcNT3 (one of the GlcNAcTs responsible for the synthesis of the core 2 O-glycan structures) and B3GNT3 (responsible for the synthesis of the extended core 1 O-glycan structure) were found to be markedly increased in the adenocarcinoma tissues." (PMID 26042789, 2015).
B3GNT3 also shares sentences with these, for which no sentence is quoted: endometrial cancer (1 paper); esophageal cancer (1); gynecologic cancers (1); infection (1); influenza (1); invasive ductal carcinoma (1); non-small cell lung carcinoma (1); ovarian carcinoma (1); pancreatic ductal adenocarcinoma (1); prostate carcinoma (1); viral infections (1).